SNRPA (small nuclear ribonucleoprotein polypeptide A)
Description:
Component of the spliceosomal U1 snRNP, which is essential for recognition of the pre-mRNA 5' splice-site and the subsequent assembly of the spliceosome. U1 snRNP is the first snRNP to interact with pre-mRNA. This interaction is required for the subsequent binding of U2 snRNP and the U4/U6/U5 tri-snRNP. SNRPA binds stem loop II of U1 snRNA. In a snRNP-free form (SF-A) may be involved in coupled pre-mRNA splicing and polyadenylation process. May bind preferentially to the 5'-UGCAC-3' motif on RNAs.
Synonyms: U1-A; U1A; Mud1
Tractability: Small molecule: a structure with a bound ligand is known. PROTAC: ubiquitination databases record sites on it; its protein half-life has been measured.
Gene: Protein-coding gene on chromosome 19 (40,750,585 to 40,765,393, forward strand). Ensembl gene ENSG00000077312.
Subcellular location: Nucleus
Subcellular location (Human Protein Atlas): Nucleoplasm
Pathways (Reactome):
Metabolism of RNA: mRNA Polyadenylation; mRNA Splicing - Major Pathway
Gene Ontology:
Molecular function: DNA binding; identical protein binding; protein binding; RNA binding; U1 snRNA binding; nucleic acid binding; U1 snRNP binding
Biological process: mRNA splicing, via spliceosome; spliceosomal snRNP assembly
Cellular component: nucleoplasm; precatalytic spliceosome; spliceosomal complex; U1 snRNP; nucleus; spliceosomal snRNP complex
Genetic constraint (gnomAD): Loss-of-function variants: 9 observed, 22.09 expected, observed/expected ratio (o/e) 0.41, 90% interval 0.25 to 0.71. The upper end of that interval is the gene's LOEUF score, 0.71, which puts it in group 2 of 6, group 1 being the genes least tolerant of losing a copy. Missense variants: 256 observed, 366.35 expected, observed/expected ratio (o/e) 0.7, 90% interval 0.63 to 0.77. Synonymous variants: 155 observed, 143.48 expected, observed/expected ratio (o/e) 1.08, 90% interval 0.95 to 1.23.
Homologues: Orthologues: chimpanzee SNRPA (99% identical), macaque SNRPA (99% identical), dog SNRPA (99% identical), guinea pig SNRPA (99% identical), rat Snrpa (99% identical), pig SNRPA (98% identical), mouse Snrpa (96% identical), tropical clawed frog snrpa (83% identical), zebrafish snrpa (83% identical), rabbit SNRPA (77% identical), Drosophila melanogaster snf (54% identical), Caenorhabditis elegans rnp-3 (39% identical), and 1 more. Paralogues in human: SNRPB2 (55% identical).
Diseases named in the same sentence as SNRPA in open-access papers:
SNRPA is named in the same sentence as 24 diseases in open-access papers, as found by Europe PMC text mining. Sharing a sentence is not in itself a finding about the gene and the disease. The quoted sentences say what the papers report.
gastric cancer (8 papers, 2019 to 2025). A primary or metastatic malignant neoplasm involving the stomach. "SNRPA is a component of the U1 small nuclear ribonucleoprotein complex, and its expression is correlated with poor outcomes in patients with gastric cancer." (PMID 40768895, 2025). "In gastric cancer, the higher expression of SNRPA promotes gastric cancer cell development by activating NGF expression." (PMID 39845190, 2024). "In spite of a study that has confirmed nerve growth factor (NGF) gene acts as a functional downstream effector of SNRPA and is essential for SNRPA modulated gastric cancer cells growth." (PMID 35392763, 2022). "Circ_0009910 is a target for the treatment of gastric cancer, and can promote the proliferation, metastasis, and glycolysis of gastric cancer through the miR361-3p/SNRPA axis." (PMID 36438836, 2022). "Previous studies have confirmed that SNRPA was considered a tumor enhancer that can promote the tumorigenesis and progression of lung cancer, gastric cancer, cervical cancer and colorectal cancer." (PMID 35860579, 2022). "The upregulation of SNRPA expression is observed in gastric carcinoma (GC) and SNRPA expression increasing or inhibition of SNRPA results in reinforced or repressed growth phenotype of GC cell." (PMID 35392763, 2022). "Recently, SNRPA has been identified as potential oncogene in gastric cancer (GC), with its expression in tumor tissues being a factor for proliferation efficiency." (PMID 31581454, 2019). "Even though it does not appear correlated to a neurological defect, SNRPA is highly expressed in lung adenocarcinoma (LUAD) and lung squamous cell carcinoma tissue (LUSC), as well as the progression of gastric cancer (GC)." (PMID 37446229, 2023).
hepatocellular carcinoma (6 papers, 2022 to 2025). A malignant tumor that arises from hepatocytes. "In addition, higher levels of SNRPA have been associated with both shorter OS and shorter recurrence-free survival in patients with hepatocellular carcinoma." (PMID 40768895, 2025). "Previous studies have shown that SNRPA promotes an EMT-like process in hepatocellular carcinoma cells by activating the NOTCH1/Snail pathway, thereby accelerating metastasis." (PMID 39845190, 2024). "As for tumor progression, an early report has manifested that SNRPA expression is abnormally elevated in hepatocellular carcinoma (HCC)." (PMID 35392763, 2022). "Correlation between SNRPA protein expression and clinicopathologic features in 161 patients with hepatocellular carcinoma." (PMID 35860579, 2022). "The qRT-PCR results showed that TOMM40L, SNRPA, ILF3, CPSF6, and NUP205 were remarkably highly expressed in hepatocellular carcinoma." (PMID 37745063, 2023).
lung adenocarcinoma (4 papers, 2020 to 2024). A carcinoma that arises from the lung and is characterized by the presence of malignant glandular epithelial cells. "In summary, the SNRPA gene was identified as a potential prognosis biomarker of lung cancer, especially lung adenocarcinoma, which sheds new light on the association between the spliceosomal complex component and tumorigenesis." (PMID 33552128, 2020). "Through analyzing the datasets within TCGA and GEO databases, our study aimed to investigate the potential role of SNRPA expression, modification, or genetic mutation in the prognosis of lung adenocarcinoma (LUAD) and lung squamous cell carcinoma (LUSC) of NSCLC." (PMID 33552128, 2020). "The results of in vitro cellular experiments indicate that SNRPA plays an important role in the development and progression of lung adenocarcinoma." (PMID 39845190, 2024). "The potential role of SNRPA phosphorylation at the S115 site in the pathological mechanism of lung adenocarcinoma merits more experimental evidence." (PMID 33552128, 2020). "This suggested the potential role of SNRPA DNA methylation in the tumorigenesis of lung adenocarcinoma." (PMID 33552128, 2020). "Through the CPTAC database with protein expression datasets, we observed a highly expressed SNRPA protein in the primary lung adenocarcinoma tissues (p = 4.7e−27), compared with normal tissues." (PMID 33552128, 2020). "When compared to the normal control tissues, we observed a higher mRNA expression level (p = 1.0e−12), and a lower promoter methylation level (p = 5.4e−08) of SNRPA is in the primary lung adenocarcinoma tissues." (PMID 33552128, 2020). "SNRPA was highly expressed in the tissues of lung adenocarcinoma (LUAD) and lung squamous cell carcinoma tissue (LUSC), compared with control tissues." (PMID 33552128, 2020). "In this study, we found that interfering with SNRPA expression could significantly inhibit the proliferation, migration, and invasion process of lung adenocarcinoma cells by in vitro cellular experiments." (PMID 39845190, 2024). "This suggests that SNRPA plays an essential role in lung adenocarcinoma occurrence and development." (PMID 39845190, 2024). "Together, these analyses suggest that SNRPA plays a critical function in the proliferation, migration, and invasion of lung adenocarcinoma and that disrupting the expression of SNRPA could effectively impede these processes in lung adenocarcinoma." (PMID 39845190, 2024). "SNRPA may function distinctively in the pathogenesis of lung adenocarcinoma and lung squamous cell carcinoma tissue." (PMID 33552128, 2020). "Both the knockout or the knockdown of SNRPA via CRISPR/Cas9 and shRNA techniques can reverse the resistance of cisplatin‐resistant lung adenocarcinoma (LUAD) cells to cisplatin." (PMID 39555714, 2024). "Thus, SNRPA may be a novel prognostic biomarker of lung adenocarcinoma." (PMID 33552128, 2020). "In addition, in vitro cellular experiments demonstrated that SNRPA plays an essential role in the occurrence and development of LUAD and can serve as a potential biomarker for lung adenocarcinoma." (PMID 39845190, 2024).
glioma (3 papers, 2022 to 2024). A benign or malignant brain and spinal cord tumor that arises from glial cells (astrocytes, oligodendrocytes, ependymal cells). "LINC01088 physically binds SNRPA and SNRPA is implicated in the tumor-promoting properties of LINC01088 in glioma." (PMID 35392763, 2022). "Further rescue experiments confirmed that linc01088 can physically interact with Small Nuclear Ribonucleoprotein Polypeptide A (SNRPA) and regulate the expression of SNRPA at the transcriptional level, thereby inducing the growth of glioma cells." (PMID 38967893, 2024). "Overall, this study verified the function and mechanism of the LINC01088/SNRPA regulatory axis in glioma." (PMID 35392763, 2022). "As a result, LINC01088 effectively induces glioma cell growth and invasion in an SNRPA-dependent manner, and SNRPA mediated the pro-tumorigenic efficacy of LINC01088." (PMID 35392763, 2022). "Analogous to LINC01088 inhibition, attenuation of SNRPA expression had a suppressive effect in glioma cells clonogenic and invasive phenotype." (PMID 35392763, 2022). "Mechanistically, LINC01088 exerted the pro-oncogenic functions through binding with SNRPA and transcriptionally regulating SNRPA mRNA in glioma." (PMID 35392763, 2022). "Phenotypic analysis ascertained that LINC01088 substantively aggravated glioma cell progression in an SNRPA-dependent manner, and SNRPA played a pivotal part in the tumor-promoting properties of LINC01088." (PMID 35392763, 2022). "In sum, these observations disclosed that SNRPA is an essential downstream factor for LINC01088 exerting cancer-promoting actions in glioma." (PMID 35392763, 2022). "Our findings revealed a novel mechanism by which LINC01088 exerted pro-oncogenic functions through binding with SNRPA and transcriptionally regulating SNRPA mRNA in glioma." (PMID 35392763, 2022). "In addition, among central nervous system tumors, LINC01088 exerts pro-oncogenic activities in glioma via binding to SNRPA and regulating SNRPA mRNA transcription." (PMID 36983670, 2023). "Furthermore, LINC01088 expression was positively correlated with SNRPA expression in serum specimens from patients with glioma." (PMID 35392763, 2022). "Our study also shown the LINC01088 level is positively correlated with SNRPA level in glioma." (PMID 35392763, 2022). "Finally, the endogenous levels of LINC01088 and SNRPA were detected using qRT-PCR in 35 paired serum specimens from glioma patients and control normally." (PMID 35392763, 2022). "Since SNRPA expression is regulated by LINC01088 in a transcriptional manner, we presumed SNRPA might be a critical element for LINC01088 in glioma progression." (PMID 35392763, 2022). "Similarly, we demonstrated that SNRPA exerts its oncogene effect in glioma." (PMID 35392763, 2022). "The results showed that LINC01088, as well as SNRPA level, were extremely higher in the glioma group than in normal." (PMID 35392763, 2022). "Importantly, qRT-PCR also displayed that in high-grade glioma, the relative levels of LINC01088 and SNRPA were higher than in low-grade glioma (p < 0.01)." (PMID 35392763, 2022).
cervical cancer (2 papers, 2020 to 2022). A primary or metastatic malignant neoplasm involving the cervix. "Interestingly, the results of our study showed that the splicing factor SNRPA exerted a protective effect against cervical cancer." (PMID 32528230, 2020).
lung carcinoma (2 papers, 2020 to 2022). "Using the available datasets of TCGA or GEO, we aimed at exploring the potential association between the SNRPA gene and lung cancer by several online tools (such as GEIPA2, MEXPRESS, Oncomine) and bioinformatics analysis software (R or GSEA)." (PMID 33552128, 2020). "Surprisingly, the high SNRPA expression was detected to be linked to a better first-progression prognosis of lung cancer cases in GEO." (PMID 33552128, 2020). "We tried to analyze whether the SNRPA gene is implicated in the etiology of lung cancer through immune cell infiltration." (PMID 33552128, 2020). "Based on the datasets of TCGA-LUAD and TCGA-LUSC cohorts, we analyzed the expression level of SNRPA between lung cancer and the para-carcinoma tissues." (PMID 33552128, 2020). "In terms of lung cancer type, the high expression of SNRPA was related to the low rates of OS (p = 2.0e−13), FP (p = 3.1e−05), and PPS (p = 0.011) for LUAD cases." (PMID 33552128, 2020). "Next, we analyzed the potential relationship between SNRPA expression pattern and the clinical prognosis of lung cancer cases." (PMID 33552128, 2020). "Besides, we note that the associations between high SNRPA expression and poor OS, FP, and PPS prognosis of lung cancer patients were mainly detected in the pathological stage I group, suggesting the potential role of SNRPA in the early stages of lung cancer." (PMID 33552128, 2020). "Besides, SNRPA expression in lung cancer was negatively correlated with the infiltration level of M2 macrophage but positively correlated with that of Follicular B helper T cells, in both LUAD and LUSC." (PMID 33552128, 2020). "Also, given a low methylation level of SNRPA, the DNA methylation factor may slightly contribute to the complicated mechanisms of SNRPA in lung cancer." (PMID 33552128, 2020). "We first enrolled all lung cancer cases (n = 483 for LUAD; n = 486 for LUSC) as the “Tumor” group and observed a higher expression level of SNRPA in the “Tumor” group, compared with the “Control” group." (PMID 33552128, 2020). "The factor of smoking history may not be involved in the mechanism of SNRPA in the pathogenesis of lung cancer." (PMID 33552128, 2020). "There was a positive correlation between SNRPA high expression and the worse survival prognosis of lung cancer cases in the subgroups of “female,” “exclude those never smoked,” “only those never smoked,” “pathologic stage I,” and “only surgical margins negative” (all HR > 1, p < 0.05)." (PMID 33552128, 2020). "Thus, the “smoking” factor may not be essential for the involvement of SNRPA in the pathogenesis of lung cancer." (PMID 33552128, 2020).
prostate carcinoma (2 papers, 2020 to 2025). A carcinoma that arises from epithelial cells of the prostate gland. "Bioinformatics analyses indicate a positive correlation between SNRPA overexpression and the aggressiveness of prostate cancer, with high levels linked to poor outcomes." (PMID 41354732, 2025). "Bioinformatics analyses established a positive correlation between SNRPA overexpression and prostate cancer aggressiveness, with patients exhibiting high SNRPA levels demonstrating poor clinical outcomes." (PMID 41354732, 2025). "Single-cell RNA sequencing data further supported the involvement of SNRPA in prostate cancer pathogenesis by revealing enriched expression within cancer cells." (PMID 41354732, 2025). "In addition, paired tissue analysis showed that SNRPA expression was significantly increased in prostate cancer tissues (“Tumor”) compared to that in the paired normal prostate tissues (“Normal”)." (PMID 41354732, 2025). "These scRNA-seq results again shows upregulation of SNRPA in prostate cancer cells." (PMID 41354732, 2025). "The bioinformatics analyses suggested a positive correlation between SNRPA expression and genes involved in oxidative phosphorylation (OXPHOS) and ATP synthesis in prostate cancer cells." (PMID 41354732, 2025). "The prostate adenocarcinoma dataset within The Cancer Genome Atlas (TCGA-PRAD) shows that SNRPA expression was significantly upregulated in prostate cancer tissues (“Tumor”) compared to normal prostate tissues (“Normal”)." (PMID 41354732, 2025). "Importantly, compared to castration-sensitive prostate cancer (CSPC) tissues, CRPC tissues exhibited significantly higher mRNA levels of SNRPA, NDUFS8, and NDUFS9, as well as increased ATP contents and mtDNA levels." (PMID 41354732, 2025).
adenocarcinoma in situ (1 paper, 2024). A lesion in which the normally situated glands are partially or completely replaced by atypical cells with malignant characteristics. "In adenocarcinoma in situ (AIS) subtype sections, SNRPA was widely expressed in the Cancer, Normal epithelium, Stromal, and Lymph regions." (PMID 39845190, 2024).
chondrosarcoma (1 paper, 2022). A malignant cartilaginous matrix-producing mesenchymal neoplasm arising from the bone and soft tissue. "GAPDH and other proteins whose secretion was augmented in response to hypoxia, including CNBP and SNRPA, could represent proteomic signatures of chondrosarcoma and could be developed as chondrosarcoma biomarkers." (PMID 35893766, 2022).
colon cancer (1 paper, 2019). "Among them, MAT2A and SNRPA were found to be involved in cell growth, with studies showing increased MAT2A expression in human colon cancer being implicated in the pathogenesis of colon cancer." (PMID 31581454, 2019).
ischemic cardiomyopathy (1 paper, 2025). Ischemic cardiomyopathy is a cardiomyopathy in which a weakness in the muscle of the heart due to inadequate oxygen delivery to the myocardium with coronary artery disease being the most common cause. "In a previous study, it was discovered that SNRPA in ischemic cardiomyopathy (ICM) directly binds to the 3′UTR of STAT5B and promotes its substitution for polyadenylation, a process that is coordinated with alternative splicing (AS)." (PMID 41477636, 2025).